LONRF2 (LON peptidase N-terminal domain and ring finger 2)
Synonyms: RNF192; FLJ45273
Tractability: PROTAC: ubiquitination databases record sites on it.
Gene: Protein-coding gene on chromosome 2 (100,271,875 to 100,322,501, reverse strand). Ensembl gene ENSG00000170500.
Subcellular location (Human Protein Atlas): Nucleoplasm
Gene Ontology:
Molecular function: protein binding; ubiquitin protein ligase activity; misfolded protein binding; ribonucleoprotein complex binding
Biological process: neuron apoptotic process; neuron projection development; protein quality control for misfolded or incompletely synthesized proteins
Genetic constraint (gnomAD): Loss-of-function variants: 33 observed, 48.17 expected, observed/expected ratio (o/e) 0.69, 90% interval 0.52 to 0.92. The synonymous counts are far from expectation, so gnomAD's model fits this gene poorly and the ratio says little. Missense variants: 806 observed, 786.12 expected, observed/expected ratio (o/e) 1.03, 90% interval 0.97 to 1.09. Synonymous variants: 376 observed, 305.6 expected, observed/expected ratio (o/e) 1.23, 90% interval 1.13 to 1.34.
Homologues: Orthologues: chimpanzee LONRF2 (99% identical), macaque LONRF2 (96% identical), dog LONRF2 (85% identical), pig LONRF2 (82% identical), rat Lonrf2 (78% identical), mouse Lonrf2 (77% identical), tropical clawed frog lonrf2 (50% identical), zebrafish si:ch1073-440b2.1 (33% identical), Drosophila melanogaster CG32369 (30% identical), Caenorhabditis elegans T02C1.1 (6% identical). Paralogues in human: LONRF3 (41% identical), LONRF1 (40% identical).
Diseases named in the same sentence as LONRF2 in open-access papers:
LONRF2 is named in the same sentence as 3 diseases in open-access papers, as found by Europe PMC text mining. Sharing a sentence is not in itself a finding about the gene and the disease. The quoted sentences say what the papers report.
rectal cancer (1 paper, 2022). A primary or metastatic malignant neoplasm that affects the rectum. "Similarly, we identified another lncRNA-miRNA-mRNA crosstalk between MBNL1-AS1, miR-429 and LONRF2 and found that they could significantly distinguish high-risk group and low-risk group of rectal cancer patients." (PMID 35495167, 2022).
LONRF2 also shares sentences with these, for which no sentence is quoted: psychiatric disorder (1 paper); type 2 diabetes mellitus (1).